INS (insulin)
Diseases named in the same sentence as INS in open-access papers (continued):
Sharing a sentence is not in itself a finding about the gene and the disease.
Obesity (continued). "PC:PE ratio disturbance has been implicated in obesity-associated ER stress, inflammation, decreased insulin signaling and steatohepatitis." (PMID 32752107, 2020). "HFD-induced obesity is known to be intimately related with lipid profiles, insulin resistance, adipokines, atherogenesis, and cardiac risk." (PMID 33273564, 2020). "In humans, miR-122, miR-143-3p, and miR-652-3p have also been reportedly linked with obesity and IR and implicated in the modulation of genes and protein cascades in insulin signaling." (PMID 32560220, 2020). "Secondly, the activation of PPARγ improves insulin sensitivity and blood glucose homeostasis, which is used for the treatment of obesity-associated diabetes in humans." (PMID 32102233, 2020). "Genetic knockdown of Ucp2 can prevent diet induced obesity and restore insulin sensitivity in leptin deficient ob/ob mice." (PMID 33240218, 2020). "It has been shown that obesity-induced adipose tissue metabolic disorders cause primary insulin resistance in insulin-sensitive tissues." (PMID 33841133, 2020). "In obesity, the chronic overproduction of these inflammatory mediators can cause impaired adipocyte insulin signalling, further inflammation and a continued deterioration of AT function." (PMID 33292104, 2020). "Results from the study provide insight into evening chronotype and its association with sleep alterations, social jet lag, obesity and metabolic disturbances (higher values of basal insulin, glucose, triglycerides and cholesterol)." (PMID 33028896, 2020). "In peripheral tissues, the resistance to insulin linked with obesity is perhaps the reason for the development of insulin resistance in the hypothalamus." (PMID 32272767, 2020). "IR reduces ability of the insulin to inhibit lipase, leading to a high level of free fatty acids and an increase in the risk of obesity and cardiovascular diseases in PCOS patients." (PMID 32552864, 2020). "A major goal for ameliorating diabetes and obesity is understanding the molecular biology underlying the differentiation of white and brown adipocytes to enhance sensitivity to insulin." (PMID 32471255, 2020). "Obesity is associated with higher levels of insulin and leptin, while sensitivity to these hormones is reduced." (PMID 32721994, 2020). "Although ERK1−/− mice have been shown to be more sensitive to insulin, diet-induced obesity mice and leptin-deficient (ob/ob) mice have elevated ERK activity." (PMID 32576931, 2020). "Food with high glycemic index (sugary and processed) that is widely available as part of the Western diet causes a spike in insulin which deposits glucose as fat (causing obesity with hypoglycemia and increasing hunger)." (PMID 32582754, 2020). "Previous work has reported higher fasting and postprandial glucose and insulin concentrations in carriers of obesity-risk FTO allele, yet this is eradicated when adjusted for BMI." (PMID 33348678, 2020). "PIK3 has both catalytic (PIK3CA and PIK3CD) and regulatory subunits (PIK3R1), being the last one critical for obesity studies since its expression is linked to insulin metabolism and initiation of inflammation processes." (PMID 32599690, 2020). "We also examined the associations between muscle ANGPTL4 and obesity, aerobic capacity, glucose tolerance and insulin sensitivity." (PMID 32878157, 2020). "Obesity is associated with increased Nos2 expression in insulin-sensitive tissue in rodents and humans." (PMID 32961723, 2020). "The deletion of NLRP3 or inhibition of caspase-1 in mice was shown to improve insulin sensitivity and ameliorate obesity-associated pathologies." (PMID 32751530, 2020). "In obesity-associated dysfunction during glucose metabolism, the impairment of insulin action on the peripheral organs is typically of importance, particularly at the skeletal muscles." (PMID 32121098, 2020).
Obesity (continued). "The both types of chemokines act as proinflammatory mediators and impair the insulin-stimulated glucose uptake over time and their elevated expression has been linked to obesity/T2D." (PMID 32188105, 2020). "In line with this, the area of visceral AT, deep and superficial subcutaneous AT depots decreased significantly (all P < 1 × 10−20), and obesity-associated metabolic features such as HbA1c and insulin levels clearly improved (all P < 0.01)." (PMID 33198820, 2020). "Obesity, an excessive body fat accumulation in individuals acts as a major risk factor for the development of diverse chronic diseases like impaired insulin metabolism, glycemic abnormalities, hypertension and cardiovascular diseases in future." (PMID 32027667, 2020). "It is known that HSL catalyzes the degradation of triacylglycerol and decreases in the expression of HSL are associated with insulin concentration and obesity." (PMID 33228176, 2020). "In conclusion, LNK deficiency has direct effects on insulin signaling and glucose translocation, which all collectively leads to increase glucose uptake in adipose tissue and improved insulin sensitivity in obesity." (PMID 32911464, 2020). "It appears that obesity-related circulating exosomes can impair insulin signaling pathways and associated components, increase intracellular TG content, and decrease FGF21 secretion in the hepatocytes." (PMID 32322309, 2020). "Overexpression of IGFBP-2 was associated with decreased susceptibility to obesity and improved insulin sensitivity." (PMID 32380764, 2020). "IGFBP-2 concentration has been associated with improvements in insulin sensitivity, BMI and lipid profile in obesity-related studies." (PMID 32586279, 2020). "Obesity is associated with chronic low‐grade inflammation particularly with heightened adipose inflammation and resistance to insulin." (PMID 33089074, 2020). "White adipose tissue (WAT) is the most relevant inflamed tissue caused by obesity-associated inflammation that promotes systemic inflammation and metabolic abnormalities due to suppression of insulin secretion and signaling." (PMID 32143623, 2020). "In those with a BMI above the 95th percentile, 77% remained obese in adulthood, and this obesity was associated with abnormalities in lipids, blood pressure and insulin levels." (PMID 32489796, 2020). "Next, we determined the impact of P2X7 deficiency on glucose homeostasis and insulin sensitivity in HFD-induced obesity." (PMID 33025427, 2020). "Obesity-associated chronic inflammation is known to be responsible for the impaired insulin response." (PMID 32825073, 2020). "Several studies have reported that DNA methylation levels at obesity-associated CpG sites were associated with cardio-metabolic factors such as lipids, insulin resistance, and blood pressure." (PMID 33239103, 2020). "One of the first accounts of lipid laden ATMs in human obesity was observed by Shapiro and coll., who managed to associate “AT foam cell” presence with fasting glucose and insulin levels." (PMID 32752107, 2020). "Recently, NLPR12 has been implicated in protecting against obesity by regulating the gut microbiota homeostasis, insulin-tolerance, and inflammation in mice." (PMID 32978410, 2020). "Adipokines, such as leptin and adiponectin, as well as other circulating factors such as insulin are associated with “metabolic syndrome” and have been extensively studied in obesity-linked OA." (PMID 32295649, 2020). "Obesity is well-known to be associated with elevated circulating levels of insulin, insulin-like growth factor 1 (IGF-1), leptin, and inflammation." (PMID 32454823, 2020). "Serum levels of sphingomyelin and ceramide species with distinct saturated acyl chains were associated with obesity and correlated with insulin sensitivity, liver function and atherogenic dyslipidemia." (PMID 32386512, 2020).
Obesity (continued). "It is observed that overexpression of miR-802 downregulates insulin transcription and secretion and impairs glucose tolerance, clearly indicating a functional role of miR-802 in the development of obesity-associated β cell dysfunction." (PMID 32286278, 2020). "In particular, Wistar/Sprague-Dawley rats and C57BL/6 mice fed HFD have been extensively used as a model of diet-induced obesity (DIO) to study the mechanisms of insulin resistance as they are comparatively more susceptible to metabolic impairment." (PMID 32455838, 2020). "Loci associated with obesity overlapped with genes involved in appetite and energy regulation, lipid metabolism and adipogenesis, as well as insulin secretion and action." (PMID 33088334, 2020). "A Mendelian randomization analysis showed that persons with genetically determined higher insulin secretion to oral glucose exhibited a higher body mass index (BMI), supporting a causal relationship between insulin and obesity risk." (PMID 32819363, 2020). "In order to initiate the insulin dysregulation related to T2D, the high-fat diet to animals is an effective method to induce obesity, which acts as a known risk factor for T2D." (PMID 33043040, 2020). "Obesity is associated with increased adipose tissue inflammation and changes in circulating concentrations of adipokines, which contribute to insulin resistance in fat, liver, and skeletal muscle tissue." (PMID 33376604, 2020). "In this study, treatment with AA improved symptoms of obesity‐linked metabolic syndrome, including adipocyte differentiation and elevated levels of lipids, glucose, and insulin, similar to results from previous studies." (PMID 32148789, 2020). "Obesity is a major risk factor for insulin dysregulation (ID) and a substantial health problem among equine populations worldwide." (PMID 32557899, 2020). "Accumulating evidence established that immune cells especially T lymphocyte alterations preceded the loss of insulin sensitivity in adipose tissue and contribute to the general pro-inflammatory drift observed in obesity and T2D." (PMID 32849564, 2020). "Specifically, Dio2-KO was shown to increase susceptibility to HFD-induced obesity with both adipose tissue and ectopic fat accumulation, as well as insulin resistance." (PMID 32344656, 2020). "We show that TMBIM6 deficiency alters glucose-dependent Ca2+ signaling in pancreatic β cells thereby instigating increased insulin secretion, a well-established direct cause for obesity and hepatic steatosis." (PMID 32394396, 2020). "For example, TNF secretion from adipose tissue and circulating plasma IL-6, both of which play a role in insulin-response, were highly associated with obesity-associated insulin resistance in a human cohort." (PMID 33287442, 2020). "We have shown that lower adipose tissue ACE2 expression was associated with diabetes and obesity status, increased serum fasting insulin and triglyceride levels, BMI, and with increased macrophage infiltration in adipose tissue, a marker of inflammation." (PMID 32817962, 2020). "Adipose tissue macrophages (ATMs) surrounding dead adipocytes cause obesity-induced inflammation and secrete pro-inflammatory cytokines leading to local insulin resistance in adipose tissues." (PMID 32582032, 2020). "Obesity is a major determinant of type 2 diabetes risk, primarily through its adverse effects on insulin sensitivity." (PMID 33004989, 2020). "Intermittent fasting in an animal study reduced basal blood glucose and basal insulin, and increased insulin sensitivity, improving risk factors for obesity and cardiovascular disease." (PMID 32784810, 2020). "The equine metabolic syndrome (EMS) is determined by obesity, insulin dysregulation (ID) and a predisposition to laminitis." (PMID 32321549, 2020). "Additional studies are required to clarify the precise mechanisms and establish the causal effects of systemic inflammation and obesity on insulin sensitivity." (PMID 33116232, 2020).
Obesity (continued). "Obesity is frequently associated with higher circulating levels of insulin, with subsequent increased ovarian androgen production." (PMID 32442310, 2020). "On the other hand, an increased peripheral insulin level is associated with obesity through the adipostat mechanism." (PMID 32272767, 2020). "In general, most animal studies and studies of human obesity have noted that increased systemic acetate leads to weight loss and improved insulin sensitivity." (PMID 33304273, 2020). "Generally, obesity is associated with substantial metabolic and endocrine abnormalities, including alterations in sex hormone metabolism, insulin and insulin-like growth factor (IGF) signaling, and adipokines or inflammatory pathways." (PMID 32197341, 2020). "Mice deficient in CerS6 were protected from HFD-induced obesity, showed improvements in glucose tolerance and insulin sensitivity, and increased energy expenditure coupled with higher fat oxidation in brown adipose tissue and liver." (PMID 32455838, 2020). "lactis strains have been shown to improve cardiometabolic risk factors in adult subjects with obesity by decreasing central adiposity and insulin resistance." (PMID 33066107, 2020). "Taken together, moderate to high normal levels of insulin in metabolic healthy persons appear to be a risk factor for the development of obesity." (PMID 32819363, 2020). "FTO (fat mass and obesity-associated), a gene associated with the common forms of obesity and with IR in T2D, modulates insulin activity and BMI." (PMID 33142938, 2020). "In mice with Hp deficiency, insulin signaling is affected in those cells that overexpress Hp if obesity is present, in particular, visceral adipose tissue, and to a much lesser extent the liver and muscle." (PMID 32695161, 2020). "Intervention studies are required to elucidate the causal relationship between FA composition and the metabolic profile, as well as the specific roles of individual FAs and total FA groups in mediating obesity-associated impairment of insulin sensitivity." (PMID 32486525, 2020). "Results have revealed that insulin regulated traffic of IRAP toward membrane fraction in adipocytes is disturbed by monosodium glutamate-induced obesity and IRAP deficiency in mice fed high-fat diet lead to prevention of development of obesity." (PMID 33344504, 2020). "In rodent models of obesity, microbiota disruption has been associated with alteration of the intestinal barrier, endotoxemia, inflammation grade, and insulin sensitivity." (PMID 33102570, 2020). "Since such small increases of systemic insulin concentrations are enough for favoring adipogenesis, fasting and diurnal insulin levels are a determinant of obesity risk." (PMID 32819363, 2020). "Post-prandial glucose and insulin dysregulation are independent risk factor for obesity and cardiovascular diseases." (PMID 33553233, 2020). "In this regard, it was previously reported that HFD-induced obesity causes insulin insensitivity and reduced leptin secretion, resulting in decreased appetite in mice." (PMID 33003300, 2020). "Another hub, BRAP, has a polymorphism associated with obesity and other metabolic traits, which can play a role in effecting insulin signaling and aging." (PMID 32205467, 2020). "While the pathophysiology of hypertriglyceridemia remains poorly understood, the mechanism of hypertriglyceridemia in the setting of obesity has been linked to insulin resistance." (PMID 33324553, 2020). "Another metabolic feature often associated with obesity is insulin resistance, which leads to increased plasma levels of both glucose and insulin." (PMID 33170123, 2020). "T2DM is a pathological condition, often associated with obesity, characterized by impairment of insulin secretion and/or function." (PMID 33536924, 2020). "Lipid overload and lipid toxicity caused by obesity affect insulin sensitivity of various organs by interfering with the insulin signal transduction pathway." (PMID 33841133, 2020).
Obesity (continued). "Patients with LEOPARD syndrome-related SHP2 mutations exhibit resistance to diet-induced obesity, an improved overall metabolic profile, and insulin hypersensitivity." (PMID 32576931, 2020). "Other mechanisms include insulin resistance, excessive lipid deposition oxidative stress caused by obesity." (PMID 33228616, 2020). "Obesity was associated with higher systemic levels of fasting lipids, glucose, and insulin levels in both genders." (PMID 32180562, 2020). "Particularly, chronic inflammatory reactions which takes place in adipose tissues contribute to the obesity associated insulin insensitivity." (PMID 32027667, 2020). "Since both cytokines and insulin in the brain regulate synaptic plasticity, learning and memory, neuroinflammation and neuronal insulin resistance have been proposed to be involved in obesity-associated brain impairment." (PMID 31991770, 2020). "Body fat loss and increased insulin sensitivity are the most effective and natural methods of reversing obesity-associated inflammation and leptin downregulation, and thus, adiponectin upregulation." (PMID 31121868, 2019). "These confirm the crucial regulatory role of Mfn2 in insulin signaling and glucose homeostasis associated with obesity and T2D." (PMID 31551926, 2019). "Its involvement in energy metabolism as an insulin-sensitizing, anti-inflammatory, and anti-atherogenic molecule is largely admitted and obesity and insulin-resistant states have been associated with reduced plasma adiponectin concentrations." (PMID 31382403, 2019). "The results indicate that microbial intervention, particularly with L. brevis DSM32386, improved glucose homeostasis by attenuating diet-induced obesity associated hyperglycaemia and insulin insensitivity." (PMID 31704943, 2019). "Different studies based on mouse models indicate that low concentrations of GABA are associated with anxiety-like behavior, insulin resistance, energy expenditure imbalance, and weight gain in overweight and obesity (41, –, 44)." (PMID 31138673, 2019). "Using our stable isotope method, which we have now validated in multiple tumor cell types, we show here that three obesity-associated tumor cell lines respond to insulin by increasing glucose oxidation relative to total mitochondrial oxidation." (PMID 31188872, 2019). "High plasma free fatty acid concentrations are typically linked with many insulin-resistant states, including obesity and NIDDM." (PMID 30678306, 2019). "Obesity is also associated with a decrease in pituitary GH secretion but an increase in the production of IGF-I in response to GH probably due to the insulin-induced increase in GH-receptors on hepatocytes." (PMID 30809194, 2019). "Obesity is associated with pro-inflammatory adipokines stimulation, estrogen and progesterone imbalance as well as dysregulation of insulin and insulin-like growth factor activity, which collectively contribute to endometrial proliferation and carcinogenesis." (PMID 31245287, 2019). "It is caused either by deficiency in insulin secretion or degradation of secreted insulin, which is the result of cell alterations caused by many internal and external factors, such as obesity, sedentary lifestyle, and oxidative stress." (PMID 31547166, 2019). "Nlrp3 and ASC (Pycard) deficient mice were also protected against obesity-induced systemic metabolic dysregulation, as well as lipid accumulation and impaired insulin signaling in hepatic and cardiac tissues." (PMID 31379826, 2019). "In the subgroup analysis including prediabetic individuals with obesity, circulating acetate was negatively associated with peripheral insulin sensitivity." (PMID 31467327, 2019). "In summary, our studies add Piezo1 to a growing list of ion channels that are implicated in regulating insulin sensitivity, glucose metabolism and energy expenditure in obesity." (PMID 31263454, 2019).